CD4 (CD4 molecule)
Diseases named in the same sentence as CD4 in open-access papers (continued):
Sharing a sentence is not in itself a finding about the gene and the disease.
cancer (continued). "MACC1 expression levels were significantly correlated with immune invasion (B cells, CD4+ T cells, CD8+ T cells, neutrophils, macrophages, and dendritic cells) and most immune markers in more than two dozen cancers studied, but the nature of this correlation varied between cancer types." (PMID 36979146, 2023). "T cells, particularly CD8+ T cells, are considered as a major player in cancer immunotherapy; however, the roles of CD4+ and CD8+ T cells in anti-PD-L1 therapy are not very clear." (PMID 36969495, 2023). "CD4+ and CD8+ T lymphocytes and NK cells are the most critical cells involved in the control of tumor development, although they employ different mechanisms to recognize and eliminate cancer cells." (PMID 36672279, 2023). "In CCA, mature DCs surrounded by CD4+ and CD8+ cells are observed at the cancer periphery, indicating that DCs might function as a bridge between the innate and the adaptive immune response, which may reflect immune exclusion in the TME." (PMID 37138880, 2023). "To further unravel the potential predictive value of PCSK9 gene alterations for ICI treatment, we then investigated the relationship between PCSK9 alterations and six common immune infiltrates (B cells, CD4+ T cells, CD8+ T cells, macrophages, neutrophils, and DCs) across multiple cancer types." (PMID 37860186, 2023). "In addition to NUSAP1 expression levels, we also observed the effect of NUSAP1 mutations on the infiltration of six immune cells (B, CD8+T, CD4+T, macrophages, neutrophils, and dendritic cells) into the TME of 31 cancer types." (PMID 37781040, 2023). "In contrast, markers associated with suppressive populations of myeloid cells (CD163, B7-H3, VISTA) and T cells (CD4, LAG3, Tim-3) were expressed at a higher level in CD45+ segments in the ‘surrounding stromal leukocyte’ regions (cf. ‘immune-rich cancer cell islet’ regions)." (PMID 37046826, 2023). "We analyzed immune cell infiltration in CAD and cancer patients, and the analysis of immune infiltration in CAD showed a significant difference in T cells CD4 naïve in CAD and a significant positive correlation between RBP1 and immune correlation with T cells CD4 naïve." (PMID 36970364, 2023). "Therefore, harnessing the full potential of CD4+ and CD8+ T cells is an increasing necessity in cancer immunotherapy." (PMID 38328405, 2023). "Furthermore, the use of a CD4+ T cell activator peptides like PADRE, can induce CD4+ T cells activity which enhance the antitumor activity of CD8+ T cells and anti-cancer vaccine's efficiency." (PMID 37037839, 2023). "In addition, CD57+ terminally differentiated effector T cells were present in the three cancer types, with a slight increase of CD57+CD4+ T cells in HCC compared to PDA." (PMID 36798126, 2023). "Thus, knockdown of CHSY1 suppressed CD8+ T cell exhaustion and enhanced the expression of CD4+ T and CD8+103+T cells to kill cancer." (PMID 37749638, 2023). "Highly proliferative CD4- and CD8-activated T cells, activated B cells, γδIFNγ cells, cancer cells, activated DCs, M1-like TAMs, and intratumoral myeloid cells rely heavily on glucose and glutaminolytic metabolism, preferentially using aerobic glycolysis over TCA-coupled OXPHOS for ATP production." (PMID 37568713, 2023). "The biological effects and functions of CD4+ T cell-derived EVs in cancer are still not fully understood." (PMID 37569887, 2023). "By using this CD4-2D3 cell line, we will be able to standardize the method to evaluate TCR functional avidity of HLA class II-restricted TCRs and select the best TCRs for developing adoptive TCR-T cell therapy against cancer and infectious disease." (PMID 36939853, 2023). "We found that the mean serum PD-L1 levels and PD-1 positive rate for peripheral CD4+ T cells and CD8+ T cells in patients with cancer were significantly higher than those in healthy donors (p<0.01, p<0.05 and p<0.05, respectively), which were consistent with previous reports." (PMID 37266424, 2023).
cancer (continued). "CD3+T lymphocytes, CD4+T lymphocytes, and CD8+T levels are often altered in cancer patients." (PMID 37200633, 2023). "The nonmalignant cells included CD4+ T cells, CD8+ T cells, T cells, NK cells, macrophages cells, B cells, cancer-associated fibroblast (CAF) cells, and endothelial cells." (PMID 37026000, 2023). "In this group of patients, a rich CD20+ cell infiltration cannot be recognized as enough to secure tissues for cancer recurrence because the CD4+ cells are dysfunctional and are not able to induce the proper cytotoxicity of other cells." (PMID 38067231, 2023). "The injection of nanoparticles could improve the vascular normalization, recruitment CD4+ and CD8+ T cells, reduce the Tregs, induce cancer cell apoptosis, and alter the aberrant TME." (PMID 36903458, 2023). "Classically, DP T cells are considered as a developmental stage in the thymus, before maturation as either CD4+ or CD8+ SP cells, but have been described in the peripheral blood and tissues in various settings, including in human cancers and some infectious diseases." (PMID 37529610, 2023). "However, further analysis showed that the percentage of PD-1+ CD45+ cells, PD-1+CD3+ T cells, PD-1+CD3+CD4+ Th cells, PD-1+CD3+CD8+ CTL varied among major cancer types." (PMID 38102684, 2023). "Cancer treatments may also interact with ART, leading to reduced efficacy or impaired CD4 recovery and function." (PMID 37476029, 2023). "The CD4+/CD8 + ratio is prognostic for cell immunity function and cancer patient outcome." (PMID 37189020, 2023). "The neoantigen vaccination derived from RNA-seq and whole-exome sequencing datasets that were currently of interest to major pharmaceutical companies, the neoantigens recognized by CD4 T cell and MHC class II-restricted manner played a vital role in the recovery of cancer patients." (PMID 37063862, 2023). "For cancer patients, the established percentage reference range of PD-1+CD45+ cells, PD-1+CD3+ T cells, PD-1+CD3+CD4+ Th cells and PD-1+CD3+CD8+ CTL were 11.2% (95% CI 10.8%-11.6%), 15.5% (95% CI 14.7%-16.0%), 15.4% (95% CI 14.9%-16.0%) and 14.5% (95% CI 14.0%-15.5%), respectively." (PMID 38102684, 2023). "To study the correlation between DTL and immune infiltration levels, we downloaded the score data of six immune infiltrating cells of different cancers from the TIMER database, including B cells, CD4 + T cells, CD8 + T cells, dendritic cells, macrophages and neutrophils." (PMID 37038185, 2023). "Compared with Omicron-infected non-cancer-afflicted subjects, total T-cell count, total T cell%, CD4+ T-cell count, and CD8+ T-cell count in Omicron-infected cancer patients were decreased (P <0.0001, P <0.001, P <0.0001, and P <0.001), while total B cell% was increased (P <0.01)." (PMID 37035158, 2023). "Therefore, depleting CD4+ T cells would promote CD8+ T cell exhaustion similar to chronic antigen stimulation models (i.e. chronic viral infection, cancer)." (PMID 37528458, 2023). "These indicated that adaptive immunity, including cytotoxic CD8 T-cells and helper CD4 T-cells with Th1 signature (IFNG, IL12, IRF1), might arise before the carcinoma stage." (PMID 36672367, 2023). "The results showed that CD4 memory resting T cells, macrophages M2, and follicular helper T cells were the three immune cell subtypes most highly correlated with ZDHHC7 expression across multiple cancers." (PMID 36286021, 2022). "In both contexts, the trends match those of experimental observations—more aggressive treatments with more overall killing result from increasing CAR T-cell dose, intermediate CD4+:CD8+ ratio, increasing CAR-antigen affinity, and increasing cancer antigen density." (PMID 35903149, 2022). "We found that the proportion of CCR4+/CD3+ cells was higher, while the fraction of CD45RA−CD62L+/CD3+CD4+ cells was lower in the lesser curvature of the gastric body of patients with early GC than in those without cancer." (PMID 36569708, 2022).
cancer (continued). "Clusters of non-malignant cells were annotated as CD4 + T cells, CD8+T cells, B cells, macrophages/DC, endothelial cells (ECs), and cancer-associated fibroblasts (CAFs) based on preferentially or uniquely expressed marker genes." (PMID 35309911, 2022). "To identify genes whose expression is modulated by TEAD2 in CD4 T and B cells, we examined TEAD2 knockdown (KD) and over-expression (OE) in cancer cell lines (n = 8, respectively) from the Library of Integrated Network-Based Cellular Signatures (LINCS) Program." (PMID 35672799, 2022). "Interestingly, the levels of VPS9D1-AS1 were related to the Ca/STM ratios of CD4+ and CD8+ T cells, suggesting that VPS9D1-AS1 prevented T cells from entering cancer tissues." (PMID 36458816, 2022). "We confirmed that the number and activity of CD8+ and CD4+ T cells in tumors and DLNs of the 4T1-bearing immunocompetent model were both increased by the combined administration of TEM and anti-PD-L1 antibodies, thereby exhibiting anti-cancer effects." (PMID 36077620, 2022). "Moreover, ZEB2 correlates with the infiltration levels of CD4+T cells in 20 cancer types, CD8+T cells in 24 cancer types, B cells in 18 cancer types, neutrophils in 29 cancer types, macrophages in 26 cancer types, and dendritic cells in 28 cancer types." (PMID 35723302, 2022). "Median CD4 cell count and nadir CD4 cell count at the first diagnosis of each cancer type, or at the last available visit for patients with no cancer diagnosed during the study period, were 601 [IQR: 413–810] and 223 [IQR: 97–350] cells/mm3, respectively." (PMID 35333883, 2022). "In addition, pan–cancer–based immune cell infiltration analysis also revealed that CYFIP2 is closely related to T–cell CD8+, T–cell CD4+ and neutrophils." (PMID 35898498, 2022). "In the R_cancer patients, the proportions of ‘T cell CD8’, ‘T cells CD4 naïve’, ‘T cells follicular helper’, ‘Mast cells resting’ were significantly higher and ‘B cells memory’, ‘macrophages M0’ were lower than in L_cancer patients (Wilcoxon test, all P < 0.05)." (PMID 36419007, 2022). "CEACAM1 is primarily expressed on cancer cells but can also be expressed on CD8+ and CD4+ T cells." (PMID 35205776, 2022). "In the first step, immune cells attempt to recognize and eliminate the cancer cells, which can be achieved initially via CD8+ and CD4+ T-cells, NK cells, as well as T-helper 1 cells, and subsequently via the formation of antibodies against the antigens on the surface of cancer cells." (PMID 36362398, 2022). "Moreover, correlation analysis hinted at a negative correlation of TMEM59L expression with CD8 T cells, activated CD4 T cells, and several immunomodulators, including IDO1, TIGIT, PD-L1, CTLA-4, and BTLA in various cancers." (PMID 36618425, 2022). "Indeed, the longer effector potency of CD4+ T cells could be explained by the lower susceptibility of these cells to exhaustion in addition to their extensive capacity to produce more IFN-γ and TNF and to proliferate upon cancer cells challenge in a mouse model." (PMID 35008422, 2022). "Non-Treg CD4+ T cells constitute a heterogeneous population of cells, which can have an indirect role in cancer control by collaborating with CD8 T cells in order to enhance their killing proficiency." (PMID 36230808, 2022). "The results of this experiment demonstrated that Put induced significant downregulation of DNA damage in normal CD4+ T cells but not in cancer cells." (PMID 35163785, 2022). "Hence, RUNX3 has important roles in restraining the pathogenicity of CD4+ CTL cells in tissue inflammation and cancer development." (PMID 36231078, 2022). "Previous studies have reported that cancer vaccines in combination with IL-7 induced a higher proportion of specific CD8+ and CD4+ memory T cells in mice models bearing tumors and improve the functionality of specific CD8+ memory T cells by enhancing their IFN-γ secretion." (PMID 36389666, 2022).
cancer (continued). "The content of CD8 and CD4 maintains a dynamic balance in the healthy state of the body to ensure the normal development of the human immunologic function, but the immune function will be greatly inhibited with high content of CD8, typically in cancer tissues." (PMID 38094221, 2022). "PSAT1 expression is significantly correlated with the infiltrating of immune cells: B cells in 13 types of cancer, CD4+ T cells in 17 types of cancer, CD8+ T cells in 12 types of cancer, Neutrophil in 11 types of cancer, macrophages in 14 types of cancer and DCs in 13 types of cancer." (PMID 36105075, 2022). "However, it was negatively correlated with antitumor natural killer cancer cells (NK), NKT cells, Gamma_delta cells, exhausted cells, and CD4 T cells." (PMID 36245843, 2022). "Besides, the infiltration levels of immune killer cells, including CD4 T and CD8 T cells and activated NK cells, were inversely correlated with POC1A expression in pan-cancer." (PMID 35748773, 2022). "It is possible that NF-kB depletion might result in inadequate surveillance against noxious agents and cancer, but further elucidation of the safety consequences of rapamycin PFC nanoparticles in reducing splenic CD4+Foxp3+ cells might be prudent." (PMID 35159680, 2022). "However, several studies have demonstrated the role of CD4+ and CD8+ T cell responses to TAA vaccines in various cancer types." (PMID 36679904, 2022). "CD4-positive T cells typically do not have a cytotoxic function; however, their role in cancer has been revisited recently owing to the fact they are required for proper activation of immune responses and maintenance of immunological memory." (PMID 36361781, 2022). "Firstly, Sangerbox tools helped us identified that activated CD4+ T cells and type 2 T helper cells were the main immune pathways which were significantly correlated with high expression of LMNB1 in most of human cancer types, especially ACC, KIRP, KIRC, LIHC, LGG, PRAD, THCA and UVM." (PMID 35241075, 2022). "Thus, BTN3A receptors through their involvement in CD4+/CD8+ T cell activation and high pro-inflammatory cytokine production, are considered the main actors in immune cell infiltration and cancer treatment." (PMID 36362212, 2022). "Meanwhile, our team also found that riskhigh sufferers had a greater proportion of stimulated memory CD4 T cells, activated CD8 T cells and mast cells, etc., which confirmed the role of T cell proliferation regulators in the modulation of cancer immunocyte infiltration." (PMID 36211359, 2022). "Moreover, TIGIT expression was found to be positively related to B cell, CD4, CD8 T cell, neutrophil, macrophage and DC infiltration in most cancers based upon the TIMER algorithm." (PMID 36211383, 2022). "CD8+ cells have limited killing and proliferative capacity without cytokines produced by CD4+ cells, and lack of cancer cell killing presents spatial limitations on CAR T-cell proliferation." (PMID 35903149, 2022). "In two studies of RT, patients with squamous cell skin cancer have higher CD4+CD25+Treg than those without cancer, and have lower T cell counts and lower CD8/Foxp3 ratios." (PMID 36426347, 2022). "Peptides of these cancer-specific aberrant proteins are presented in complex with MHCI or MHCII on the cancer cell surface and can be recognized by appropriate CD8+ T cells and CD4+ T cells, inducing an immune response and tumor cell killing." (PMID 35892709, 2022). "In addition, blocking the TGF-β signal in CD4+T cells can reshape TME and inhibit cancer progression." (PMID 35677537, 2022). "Among them, the expressions of T cell CD4+ central memory, T cell CD4+ Th1, and HIF1α have the strongest negative correlation in various cancers." (PMID 35860430, 2022). "Furthermore, in our study, positive correlations were detected among peripheral PD1+CD4+T lymphocytes and each of cancer tissue PD1+CD4+, PD1+CD8+, and CD39+CD8+T cells and among peripheral and cancer tissue CD39+CD4+and CD39+CD8+ T cells." (PMID 35051220, 2022).
cancer (continued). "We hypothesize that CD4 and CD8 lymphocytes from blood of patients with different cancer should react differently to radiation and the chemotherapy and hormone therapy maybe have some impact on radiation response." (PMID 36494413, 2022). "In this latter study, RT patients without a history of cancer post-transplant had similar numbers of Treg to HV, whereas patients with cancer post-transplant had increased CD4+CD25+Foxp3+Treg." (PMID 36426347, 2022). "Live cancer cells engineered to express MHCII along with co‐stimulatory molecules could, in principle, provide a vaccination strategy to directly prime naïve CD4+ T cells against the parental tumor." (PMID 35959554, 2022). "Among the HDAC inhibitors we tested, Belinostat, Romidepsin (HDAC1 and 2), and Tubastatin (HDAC6) inhibited acetylation at H3 and H4 using cancer cells but did not affect the ability of Mtb-infected MФs to present antigen to CD4 T cells." (PMID 35590096, 2022). "We further identified CD4 displayed negative correlations in several TCGA cancers (LUSC, LUAD, STAD, and COAD), while positive correlations in other four cancer types (KIRC, THCA, BRCA, and PRAD)." (PMID 36081518, 2022). "Then, we analyzed the expression of cancer-infiltrating immunocytes in LUAD, and observed that B cell, T cell CD4+, endothelial cell, macrophages, NK cell, and uncharacterized cell exhibited a dysregulated level in LUAD samples in contrast to nontumor specimens." (PMID 35509981, 2022). "Interestingly, the results also showed that OTUD6B expression was positively correlated with memory CD4+ T cells, Th2 CD4+ T cells, and CD8+ T cells and negatively correlated with Th1 CD4+ T cells in TCGA pan-cancer." (PMID 36052059, 2022). "DCs stimulated by certain commensal bacteria may mediate CD4 + T-cell differentiation into Th1, Th2, or Th17 cells, all of which alter gut immune homeostasis and lead to IBD or cancer." (PMID 35739324, 2022). "NOL7 expression was significantly correlated with the abundance of infiltrating immune cells: CD4+ T cells in 14 types of cancer, CD8+ T cells in 16 types of cancer, B cells in 11 types of cancer, neutrophils in 16 types of cancer, macrophages in 14 types of cancer, and DCs in 18 types of cancer." (PMID 36077008, 2022). "Moreover, TIMER database was used to explore the correlation of ARPC5 expression with infiltration levels of B cell, CD4+ T cell, CD8+ T cell, neutrophil cell, macrophage cell, and DC cell in pan-cancer." (PMID 36148220, 2022). "Although Foxp3 is considered as a specific marker of CD4+ regulatory T cells, it was also reported to express in non-Treg immune cells as well as non-immune cells, including CD8+ T cells, γδ T cells, NKT cells, B cells, macrophages, and cancer cells." (PMID 35967422, 2022). "The results of this work suggest that the cytoprotective properties of PAs are associated with alternative splicing of RAD51A pre-mRNA in normal human CD4+ T lymphocytes but not in cancer cells." (PMID 35163785, 2022). "In this context, the exhaustion of CD4+ and CD8+ T cells is common in malignant tumors." (PMID 35912251, 2022). "The results of previous experiments did not allow us to answer why Put prevented the death of normal CD4+ T cells but not cancer Jurkat or K562 cells." (PMID 35163785, 2022). "Although immune cell infiltration is reduced in both cancers under conditions of high lactate metabolism, CD4 + T cell infiltration was not correlated with lactate metabolism score in TC." (PMID 35873566, 2022). "Unlike the results observed in infections and cancer, the combinations of blocking Tim-3 and PD-1 resulted in a profound reduction in Ki67 expression and the activation of CD4+T cells in LEASO." (PMID 35757718, 2022). "DMAP analysis showed a comparatively higher expression of EHMT2 during CD4+/CD8+ T-cell lineage hematopoietic commitment and supports the hypothesis of a preferential cancer dependency based on hematopoietic lineage commitment." (PMID 35710782, 2022).